CREG1 (cellular repressor of E1A stimulated genes 1)
Diseases named in the same sentence as CREG1 in open-access papers (continued):
Sharing a sentence is not in itself a finding about the gene and the disease.
Thrombocytopenia (1 paper, 2023). A reduction in the number of circulating thrombocytes. "In the present study, we show that megakaryocyte/platelet-specific Creg1-deficient mice (Creg1pf4-cre mice) develop thrombocytopenia." (PMID 37496998, 2023). "In this study, we found that CREG1 protein is expressed in platelets and megakaryocytes and was decreased in the platelets of patients with thrombocytopenia." (PMID 37496998, 2023). "In our study, we found decreased expression of CREG1 in platelets from patients with thrombocytopenia." (PMID 37496998, 2023). "A cytosine arabinoside-induced thrombocytopenia mouse model was established, and the mRNA and protein expression levels of CREG1 were found to be reduced in megakaryocytes." (PMID 37496998, 2023). "CREG1 protein levels were measured in the platelets of 10 thrombocytopenia patients and 10 control subjects, and markedly decreased in platelets from patients." (PMID 37496998, 2023). "By identifying CREG1 as an important target, we have provided a theoretical basis and new ideas for the prevention and treatment of thrombocytopenia." (PMID 37496998, 2023). "Furthermore, we showed that the expression of CREG1 was markedly downregulated at the mRNA and protein levels in megakaryocytes of mice with Ara-c induced thrombocytopenia." (PMID 37496998, 2023). "Thus, our study uncovered the role of CREG1 in the regulation of megakaryocyte maturation and thrombopoiesis, and it provides a possible theoretical basis for the prevention and treatment of thrombocytopenia." (PMID 37496998, 2023). "Our study demonstrates the important role of CREG1 in megakaryocyte differentiation and platelet production and suggests that CREG1 may be a novel target for the treatment of thrombocytopenia." (PMID 37496998, 2023).
type 2 diabetes (1 paper, 2023). "Male C57BL/6 J mice, Creg1 transgenic mice and cardiac-specific knockout mice were used to establish a type 2 diabetes model." (PMID 37658156, 2023).
cancer (4 papers, 2018 to 2025). A tumor composed of atypical neoplastic, often pleomorphic cells that invade other tissues. "These experiments support the idea that Mɸ-derived CREG1 can at least partially suppress invasive behaviors of cancer cells in complex 3D-environments." (PMID 32385587, 2021). "We also provide first in vivo evidence for tumor-suppressing functions of CREG1 in orthotopic transplantation of CREG silenced cancer cells into mouse mammary fat pad." (PMID 32385587, 2021). "This approach identified CREG1, NME2, and TSPYL5 as frequently altered across multiple cancers." (PMID 41476960, 2025). "CREG1, NME2, and TSPYL5 exhibited significant CNV across pan-cancer types." (PMID 41476960, 2025). "Next, immunohistochemistry for CREG1 in PyMT tumor sections revealed increased CREG1 staining in specimens derived either from Ctsb/Ctsz double knock-out cancers or from Ctsb single knock-outs but not in the Ctsz single knock-out." (PMID 32385587, 2021). "Combining Creg1 knock-down cancer cells and Mɸ did not boost invasive sprout numbers but caused a small but significant increase in sprout length." (PMID 32385587, 2021).
tumor (4 papers, 2009 to 2021). "Although these late reports associate CREG1 functions with downstream signaling pathways, its tumor-suppressor-like functions might reside in its binding to the cation-independent mannose-6-phosphate insulin-like growth factor 2 receptor (M6P/IGF2R)." (PMID 32385587, 2021). "This experiment is the first evidence for an impact of CREG1 expression levels on tumor growth in vivo." (PMID 32385587, 2021). "Further experiments were carried out by the addition of recombinant CREG1 to mimic macrophage secreted CREG1 in the tumor microenvironment." (PMID 32385587, 2021). "Again, a reduced abundance of CREG1 was evident in tumor lysates from mice with transgenic overexpression of human CTSB (long exposure)." (PMID 32385587, 2021). "In conclusion, we were able to establish CTSB as a key determinant of CREG1-mediated tumor growth suppression." (PMID 32385587, 2021). "We show that treatment of PyMT tumor cells with recombinant CREG1 reduced proliferation, migration, and invasion; whereas, the opposite was observed with reduced CREG1 expression." (PMID 32385587, 2021). "Conversely, cathepsin inhibition or silencing spares CREG1 from degradation and enables CREG1-mediated attenuation of tumor progression." (PMID 32385587, 2021). "Our study highlights CREG1 as a key player in tumor–stroma interaction and suggests that cathepsin B sustains malignant cell behavior by reducing the levels of the growth suppressor CREG1 in the tumor microenvironment." (PMID 32385587, 2021). "Lastly, to evaluate the influence of CREG1 on tumor progression in vivo, shCreg1 PyMT cells were orthotopically transplanted into the mammary fat pad of Rag2−/− γc−/− immunosuppressed mice." (PMID 32385587, 2021). "Here, we determined invasive strand formation depending on Creg1 knock-down in tumor cells, in Mɸ or in both cell types." (PMID 32385587, 2021). "Hitherto, one might envision that both Mɸ and tumor cells secrete CREG1, which then contributes to tumor control." (PMID 32385587, 2021). "CREG1 appears to be one of their important substrates whose cleavage supports tumor growth." (PMID 32385587, 2021). "However, CREG1 seems to have a tumor cell-autonomous effect, as silencing CREG1 in PyMT cells led to increased proliferation, migration, and invasion." (PMID 32385587, 2021). "Interestingly, CREG1 is a secreted and also lysosomal protein with previously reported tumor-suppressor-like functions." (PMID 32385587, 2021). "Therefore, increased CREG1 levels in tumor-bearing CTSB or CTSB/CTSZ knock-out mice could mediate the reduction in tumor proliferation and invasive growth that has been consistently reported for such models." (PMID 32385587, 2021). "Both CREG1 and CTSB are lysosomal proteins, subject to lysosomal sorting, and therefore potentially prone to lysosomal exocytosis in the tumor context; thus, both proteins are spatiotemporally located in the same space, strengthening the idea that such an interaction occurs in vivo." (PMID 32385587, 2021). "In this experiment, the highest CREG1 abundance was observed when both tumor cells and Mɸ lacked the proteases." (PMID 32385587, 2021).
metabolic disorders (2 papers, 2017 to 2022). "This study uncovered a novel function of CREG1 in metabolic disorders." (PMID 28459882, 2017).
CREG1 also shares sentences with these, for which no sentence is quoted: infection (5 papers); atherosclerosis (4); endothelial dysfunction (3); gastric cancer (3); adenovirus infection (2); alcoholic fatty liver disease (1); arteriosclerosis (1); arteriosclerosis obliterans (1); colorectal cancer (1); dyslipidemia (1); heart failure (1); hypertrophy (1); infarct (1); injury (1); ischemia (1); lipid metabolism disorders (1); liver cancer (1); liver disease (1); lung carcinoma (1); meningioma (1); myocardial ischemia (1); non-alcoholic fatty liver disease (1); peritonitis (1); renal dysfunction (1); thrombotic microangiopathy (1); uterine corpus endometrial carcinoma (1); vascular disorder (1).